CISD1 (CDGSH iron sulfur domain 1)
Description:
L-cysteine transaminase that catalyzes the reversible transfer of the amino group from L-cysteine to the alpha-keto acid 2-oxoglutarate to respectively form 2-oxo-3-sulfanylpropanoate and L-glutamate. The catalytic cycle occurs in the presence of pyridoxal 5'-phosphate (PLP) cofactor that facilitates transamination by initially forming an internal aldimine with the epsilon-amino group of active site Lys-55 residue on the enzyme (PLP-enzyme aldimine), subsequently displaced by formation of an external aldimine with the substrate amino group (PLP-L-cysteine aldimine). The external aldimine is further deprotonated to form a carbanion intermediate, which in the presence of 2-oxoglutarate regenerates PLP yielding final products 2-oxo-3-sulfanylpropanoate and L-glutamate. The proton transfer in carbanion intermediate is suggested to be controlled by the active site lysine residue, whereas PLP stabilizes carbanion structure through electron delocalization, also known as the electron sink effect. Plays a key role in regulating maximal capacity for electron transport and oxidative phosphorylation (By similarity). May be involved in iron-sulfur cluster shuttling and/or in redox reactions. Can transfer the [2Fe-2S] cluster to an apo-acceptor protein only when in the oxidation state, likely serving as a redox sensor that regulates mitochondrial iron-sulfur cluster assembly and iron trafficking upon oxidative stress.
Synonyms: C10orf70; ZCD1; MDS029; mitoNEET
Tractability: Small molecule: a structure with a bound ligand is known; a high-quality ligand is known; it belongs to a druggable protein family. Antibody: UniProt predicts a signal peptide or a membrane-spanning region. PROTAC: UniProt records ubiquitination sites on it; ubiquitination databases record sites on it; its protein half-life has been measured; a small molecule that binds it is known.
Gene: Protein-coding gene on chromosome 10 (58,269,151 to 58,289,586, forward strand). Ensembl gene ENSG00000122873.
Subcellular location: Mitochondrion outer membrane
Subcellular location (Human Protein Atlas): Mitochondria
Gene Ontology:
Molecular function: 2 iron, 2 sulfur cluster binding; identical protein binding; L-cysteine transaminase activity; protein homodimerization activity; pyridoxal phosphate binding
Biological process: protein maturation; intracellular iron ion homeostasis; regulation of autophagy
Cellular component: mitochondrial outer membrane; mitochondrion
Genetic constraint (gnomAD): Loss-of-function variants: 4 observed, 6.75 expected, observed/expected ratio (o/e) 0.59, 90% interval 0.29 to 1.34. That is too few expected variants to judge how well the gene tolerates losing a copy. Missense variants: 91 observed, 112.92 expected, observed/expected ratio (o/e) 0.81, 90% interval 0.68 to 0.96. Synonymous variants: 32 observed, 36.7 expected, observed/expected ratio (o/e) 0.87, 90% interval 0.66 to 1.17.
Homologues: Orthologues: chimpanzee CISD1 (100% identical), dog CISD1 (93% identical), guinea pig Cisd1 (92% identical), mouse Cisd1 (86% identical), rat Cisd1 (86% identical), pig CISD1 (85% identical), tropical clawed frog cisd1 (69% identical), zebrafish cisd1 (67% identical), rabbit CISD1 (64% identical), Caenorhabditis elegans cisd-1 (45% identical), Drosophila melanogaster Cisd2 (43% identical). Paralogues in human: CISD2 (54% identical), CISD3 (22% identical).
Diseases named in the same sentence as CISD1 in open-access papers:
CISD1 is named in the same sentence as 84 diseases in open-access papers, as found by Europe PMC text mining. Sharing a sentence is not in itself a finding about the gene and the disease. The quoted sentences say what the papers report.
breast carcinoma (15 papers, 2015 to 2025). "Prognosis analysis of breast cancers showed that CISD1 expression was negatively associated with clinical outcomes." (PMID 40389408, 2025). "CISD1 is highly expressed in breast cancer patients and independently associated with adverse clinical outcomes." (PMID 40389408, 2025). "In this work, an association between breast cancer and diabetes mellitus has been depicted through identifying the role of a ferroptosis related gene-CISD1." (PMID 36671422, 2022). "In addition to diabetes, CISD1 expression impairment is also associated with tumor growth (such as breast cancer and liver cancer) and has been considered as a potential chemotherapy target." (PMID 34692692, 2021). "The role of CISD1 in cancer was first shown in breast cancer, where CISD1 is overexpressed and suppression of CISD1 significantly reduces cell proliferation and tumor growth, and it has been further identified as a novel target for breast cancer chemotherapy." (PMID 40831536, 2025). "Building on this foundation, a recent study introduced a novel prognostic model for breast cancer, that integrates four ferroptosis-related genes (CISD1, ALOX15, CARS1, and SLC7A11)." (PMID 39867656, 2024). "Although CISD1 had been indicated that it contributed to human breast cancer proliferation by inducing tumor growth, more detailed protein–protein, protein–nucleic acid interaction information was needed." (PMID 36671422, 2022). "Our results showed that pDC, NK and Th17 and other cells were negatively correlated, while Th2, Th1 and macrophages and other cells were positively correlated with CISD1 expression in breast cancer." (PMID 36671422, 2022). "All these achievements demonstrated that CISD1 can be a promising target for both breast cancer and diabetes mellitus cure." (PMID 36671422, 2022). "In summary, an integrated analysis was performed to demonstrate the possible link between breast cancer and diabetes via regulating CISD1 and related genes." (PMID 36671422, 2022). "Based on the mean value of CISD1 gene expression, the patients with breast cancer were divided into high expression level group (n = 542) and low expression level group (n = 541)." (PMID 36671422, 2022). "CISD1 and co-expressed genes, especially shared ones with diabetes mellitus, can be the focused genes considered when addressing clinical problems in breast cancer with a diabetes mellitus background." (PMID 36671422, 2022). "Integrated bioinformatics methods were performed to examine the correlation between CISD1, co-expressed genes expression levels, and breast cancer clinical pathology features of breast cancer." (PMID 36671422, 2022). "Recent studies also revealed that high expression of CISD1 contributes to the growth of breast cancer cells by mediating iron and reactive oxygen homeostasis in mitochondria, which is believed to be a promising target for cancer therapy." (PMID 34115610, 2021). "Actually, studies have shown that CISD1 promotes breast cancer survival and proliferation by protecting the mitochondria of cancer cells from iron overaccumulation, enhancing the tolerance of cancer cells to oxidative stress, and suppressing autophagy and apoptosis." (PMID 40831536, 2025). "In addition to breast cancer, CISD1 has been demonstrated as a potential novel antileukemic drug target for refractory or relapsed B-cell acute lymphocytic leukemia." (PMID 40831536, 2025). "CISD1 was reported to be up-regulated in breast cancer and acute lymphoblastic leukemia." (PMID 40831536, 2025). "Pioglitazone has been reported to inhibit ACSL4 to protect breast cancer cells from ferroptosis, in parallel, pioglitazone functions as a stabilizer of CISD1 to inhibit mitochondrial iron uptake, which dictates another mechanism of pioglitazone in the regulation of ferroptosis." (PMID 38918793, 2024).
breast carcinoma (continued). "This study revealed that the CISD1 expression was higher in breast cancer, cholangiocarcinoma, colon cancer, esophageal cancer, head and neck squamous cell carcinoma, hepatocellular carcinoma, lung cancer, gastric cancer, and endometrial adenocarcinoma compared to the normal tissues." (PMID 35313629, 2022). "Thus, it was necessary to find out those shared genes between breast cancer and diabetes mellitus relating to CISD1 for further studies." (PMID 36671422, 2022). "However, a more elaborated molecular mechanism is needed for clarifying the interplay between breast cancer, CISD1, and diabetes mellitus." (PMID 36671422, 2022). "The result revealed that the CISD1 expression was higher in breast cancer, cholangiocarcinoma, colon cancer, esophageal cancer, head and neck squamous cell carcinoma, hepatocellular carcinoma, lung cancer, gastric cancer, and endometrial adenocarcinoma compared to the normal tissues." (PMID 35313629, 2022). "CISD1 promotes human breast cancer proliferation and confers autophagy resistance." (PMID 34059009, 2021). "Higher expression level of CISD1 was found to be associated with worse clinical outcome (P = 4E-04, log-rank test), and high expression of ATP7B was significantly associated with long survival time of breast cancer patients (P = 0.0203, log-rank test)." (PMID 33281885, 2020). "Therefore, co-expression genes of CISD1 in breast cancer were studied." (PMID 36671422, 2022). "Additionally, chemical-protein analysis had shown that a tested association between CISD1 and pioglitazone, which indicated that CISD1 might be a critical player both in breast cancer and diabetes mellitus." (PMID 36671422, 2022). "Additionally, CISD1 is overexpressed in both lung adenocarcinoma and breast cancer." (PMID 35033072, 2022). "The inclusion of these 8 genes (ALOX15, CHAC1, CISD1, CS, SLC7A11, EMC2, G6PD, and ACSF2) is highly valuable for prognostic prediction in breast cancer patients." (PMID 39867656, 2024). "The recently identified iron-sulfur proteins CISD1 and CISD2 facilitate the proliferation of breast cancer cells." (PMID 39867656, 2024). "Silencing CISD1 and CISD2 or targeting breast cancer mitochondria with the mitogen derivative MAD-28 can destabilize iron-sulfur proteins, elevate mitochondrial iron accumulation, and hinder breast cancer cell growth." (PMID 39867656, 2024). "The results indicated that EMC2, G6PD, FLT3, IFNG, ANO6, and SLC1A4 were positively correlated with ferroptosis while CISD1, TP63, and BRD4 were negatively correlated with ferroptosis in breast cancer." (PMID 34222241, 2021). "Moreover, decreased CISD1 expression and elevated 4-HNE levels from SB-T-101141 induction were notably abolished by KHSRP depletion and DFOM in breast cancer cells." (PMID 40389408, 2025).
hepatocellular carcinoma (13 papers, 2021 to 2025). A malignant tumor that arises from hepatocytes. "In human hepatocellular carcinoma cells, pioglitazone inhibits mitochondrial iron uptake and lipid peroxidation, further preventing ferroptosis by stabilizing the CISD1 iron-sulfur cluster." (PMID 40831536, 2025). "To further evaluate CISD1 expression in hepatocellular carcinoma, we detected the different expressions of CISD1 between hepatocellular carcinoma and normal tissue with TCGA LIHC data and two microarray expression data in GEO (GSE14520, GSE25097)." (PMID 35313629, 2022). "Inhibition of CISD1 results in iron accumulation and oxidative injury in mitochondria, thus contributing to erastin-induced ferroptosis in hepatocellular carcinoma cells." (PMID 36338716, 2022). "Both GEO datasets showed that CISD1 expression was significantly higher in hepatocellular carcinoma than in normal tissue." (PMID 35313629, 2022). "CISD1 expression was significantly higher in hepatocellular carcinoma than in normal tissue and hepatocytes." (PMID 35313629, 2022). "A previous study revealed that 3 ferroptosis-related genes (SLC7A11, G6PD, CISD1) in hepatocellular carcinoma were upregulated in tumor tissue, and their high expression correlated with a poor prognosis." (PMID 33672990, 2021). "The classical ferroptosis inducer erastin promoted CISD1 expression in an iron-dependent manner in human hepatocellular carcinoma cells." (PMID 34073365, 2021). "CISD1 reduces ferroptosis via iron-sulfur cluster biogenesis and was identified as prognostic ferroptosis-related genes in bladder cancer, lung cancer, and hepatocellular carcinoma." (PMID 36998462, 2023). "Meanwhile, CISD1 can be served as a prognostic biomarker in patients with hepatocellular carcinoma." (PMID 36555319, 2022). "Low CISD1 expression could contribute to the ferroptosis of hepatocellular cancer cells by iron-mediated intramitochondrial lipid peroxidation." (PMID 34277151, 2021). "Interestingly, high mRNA expression of CISD1 can impact the prognosis of hepatocellular carcinoma patients who were treated with sorafenib indicating that the CISD1 antagonist may enhance the anti-HCC effect of sorafenib." (PMID 35313629, 2022). "In human hepatocellular carcinoma (HCC) cells, CISD1 negatively regulates ferroptosis by reducing mitochondrial iron accumulation to prevent mitochondrial damage." (PMID 39872359, 2022). "In hepatocellular carcinoma, CDGSH iron sulfur domain 1 (CISD1) was found to negatively regulate ferroptosis by inhibiting mitochondrial iron uptake, lipid peroxidation." (PMID 36845727, 2023). "It is reported that in the prognosis model of hepatocellular carcinoma, the genes (NFS1, CISD1, ACSL3, NQO1, SLC7A11, GPX4) that can protect hepatocytes with ferroptosis and the genes (ACACA, CARS, G6PD, SLC1A5) that induce ferroptosis are all up-regulated in HCC, and are related to poor prognosis." (PMID 36387286, 2022).
diabetes (8 papers, 2010 to 2025). "This study aims to depict the association between the CISD1, the co-expressed genes, and diabetes mellitus to offer potential therapeutic targets for further mechanical research." (PMID 36671422, 2022). "CISD1 could associate the homeostasis of iron and ROS in neurons with mitochondrial function, which associated with several human diseases, including diabetes, that are associated with this type of iron-sulfur proteins, Wolfram syndrome 2, and neurodegeneration." (PMID 33723216, 2021). "In human, 3 different genes encode CDGSH proteins: CISD1 encodes mitoNEET (mNT), a homodimer that is anchored to the outer mitochondrial membrane (OMM) and is involved in diabetes, obesity, cancer, cardiovascular disease and neurodegeneration." (PMID 29556009, 2018). "There were 138 genes shared both in co-expressed genes with CISD1 and diabetes mellitus." (PMID 36671422, 2022). "Given that pioglitazone was a drug used in the management of type 2 diabetes mellitus, which was also identified an interaction between pioglitazone and CISD1 in this study, we speculated that CISD1, a key role in ferroptosis, might be a significant target for treating BRCA with diabetes mellitus." (PMID 36671422, 2022). "There are 138 genes shared between CISD1 co-expressed gene pool in BRCA and diabetes mellitus related genes using “diabetes” as the term for text mining." (PMID 36671422, 2022). "Thus, it was necessary to present the correlation between the co-expressed genes with CISD1 in BRCA and diabetes mellitus." (PMID 36671422, 2022). "The mitochondrial protein mitoNEET (also known as CDGSH iron-sulfur domain 1 (CISD1)) is a member of iron-sulfur protein and is involved in a variety of human pathologies including diabetes, Wolfram syndrome 2, cystic fibrosis, muscle atrophy, and neurodegeneration." (PMID 30805086, 2019).
Parkinson disease (8 papers, 2022 to 2026). A progressive degenerative disorder of the central nervous system characterized by loss of dopamine producing neurons in the substantia nigra and the presence of Lewy bodies in the substantia nigra and locus coeruleus. "While these effects of CISD1 on mitochondrial functions support its potential role in the pathogenesis of several types of diseases including Parkinson’s disease, cancers, and diabetes, the underlying molecular mechanisms remain elusive." (PMID 37626046, 2023). "We first tested the accuracy of two machine learning-built models and finally chose to use the random forest to obtain five Parkinson’s disease FRHGs (CISD1, SIRT2, NUPR1, ADAM23 and NEDD4L)." (PMID 38127902, 2023). "The top 5 genes were extracted as FRHGs in Parkinson’s disease (CISD1, SIRT2, NUPR1, ADAM23 and NEDD4L)." (PMID 38127902, 2023). "These CISD1 coexpressed genes were involved in thermogenesis, Parkinson's disease, prion disease, diabetic cardiomyopathy, non-alcoholic fatty liver disease, chemical carcinogenesis, reactive oxygen species, Huntington disease, amyotrophic lateral sclerosis, and Alzheimer's disease." (PMID 40831536, 2025). "The Yellow module yielded three FRGs in Parkinson’s disease (CISD1, ADAM23 and NEDD4L)." (PMID 38127902, 2023). "We also evaluated whether cisd-1 downregulation accelerates neurodegeneration by using the aggregation-prone nematode model for Parkinson’s disease (PD), UA196 [sid-1(pk3321); baIn33(pdat-1SID-1, pmyo-2mCherry);(pdat-1α-Syn, pdat-1GFP)]." (PMID 36774344, 2023). "Additionally, cisd-1 silencing perturbs cellular proteostasis in nematode models of Parkinson’s and Huntington’s diseases." (PMID 36774344, 2023).
glioma (5 papers, 2020 to 2025). A benign or malignant brain and spinal cord tumor that arises from glial cells (astrocytes, oligodendrocytes, ependymal cells). "In contrast, higher CISD1 expression was significantly associated with lower risk of death in GBMLGG (Glioma) (HR = 0.54, p = 5.8e-8), LGG (HR = 0.52, p = 8.3e-5), and NB (Neuroblastoma) (HR = 0.58, p = 0.01)." (PMID 40831536, 2025). "Previous studies have shown that CISD1 was related to survival of glioma, and high CISD1 expression is a marker of better outcome in glioma." (PMID 34073365, 2021). "No data on the involvement of such genesas ASCC1, ZCCHC17 (participates in biogenesisof ribosomal DNA), PLAT, CISD1,TMEM229a and RANBP3L in the development and spread ofany glioma types have been found." (PMID 39539523, 2024).
liver cancer (5 papers, 2021 to 2025). An epithelial or non-epithelial malignant neoplasm that arises from the liver. "To further investigate the expression of CISD1 in liver cancer, we verified the expression of CISD1 at mRNA and protein levels using the GEO dataset (GSE14520, GSE25097) and HPA database, respectively." (PMID 35313629, 2022). "Interestingly, stratified analysis by clinical characteristics of liver cancer patients showed that patients with low CISD1 expression had a better prognosis after treatment with sorafenib." (PMID 35313629, 2022). "In addition, the mitochondrial outer membrane protein CDGSH iron sulfur domain 1 (CISD1) was reported to reduce the sensitivity of liver cancer cells to erastin by inhibiting mitochondrial iron overload mediated lipid peroxidation, providing a new target for cancer treatment." (PMID 36406272, 2022). "In a study using HepG2 and Hep3B liver cancer cell lines, the CDGSH iron sulfur domain 1 iron-containing outer mitochondrial membrane protein (CISD1, also named mitoNEET) was shown to inhibit ferroptosis by protecting against mitochondrial lipid peroxidation." (PMID 38993645, 2024). "The results showed that CISD1 expression has positive correlations with infiltrating levels of CD8+ T cells, neutrophils, macrophages, and dendritic cells in liver cancer." (PMID 35313629, 2022). "The results showed that CISD1 expression was significantly correlated with infiltrating levels of CD8+ T cells (r = 0.139, p = 0.00724), neutrophils (r = 0.114, p = 0.0276), macrophages (r = 0.226, p = 1.06E − 05), and dendritic cells (r = 0.165, p = 0.00136) in liver cancer." (PMID 35313629, 2022).